TNF (tumor necrosis factor)
Diseases named in the same sentence as TNF in open-access papers (continued):
Sharing a sentence is not in itself a finding about the gene and the disease.
autoimmune disease (1,318 papers, 2004 to 2026). A disorder resulting from loss of function or tissue destruction of an organ or multiple organs, arising from humoral or cellular immune responses of the individual to their own tissue constituents. "Adalimumab (ADA), a TNF-α inhibitor, appears to be an effective and safe option for pediatric Crohn's disease (CD), but the potential risk of opportunistic infection and autoimmune disease is of particular concern." (PMID 41884829, 2026). "Tumor necrosis factor alpha (TNF-α), a pro-inflammatory cytokine secreted primarily by macrophages, has been associated with the pathogenesis of autoimmune diseases." (PMID 41141350, 2025). "This dual role of TNF-α underscores the need to balance its pro-inflammatory and anti-tumor functions when evaluating the long-term cancer risk associated with TNF inhibitor therapy in autoimmune diseases." (PMID 41302997, 2025). "Chronic elevation of TNF-α has also been implicated in stroke risk, particularly in individuals with pro-inflammatory conditions such as diabetes or autoimmune disease." (PMID 40869247, 2025). "In fact, the use of TNF-blocking agents has been associated with a more favorable response to pneumococcal vaccination in patients with autoimmune diseases compared to other immunosuppressive medication such as methotrexate, azathioprine or rituximab." (PMID 40004702, 2025). "Dysregulated or excessive activation of TNF-α signaling is associated with chronic inflammation, potentially leading to pathological complications such as autoimmune disorders." (PMID 40717907, 2025). "By stimulating dendritic cells, aldosterone activates CD8+ T cells and polarizes CD4+ T cells to Th17, a phenotype associated with inflammation and autoimmune disease, secondary to the production of interleukin-6 (IL-6) and tumor necrosis factor-α (TNF-α)." (PMID 40426991, 2025). "With highly effective B cell depletion therapy, this population re-emerged in the CSF of MS patients, with associated increases in myeloid TNFα expression in both CSF and blood, suggesting an important role in autoimmune disease pathogenesis." (PMID 40475455, 2025). "This case highlights the diagnostic challenge of distinguishing MS from TNF-α inhibitor-associated demyelination in patients with autoimmune disease." (PMID 41450349, 2025). "The second pro-inflammatory cue used was TNFα, a pleiotropic cytokine that can lead to chronic inflammation associated with various autoimmune diseases and inflammatory conditions." (PMID 40248812, 2025). "A recent meta-analysis reported a similar risk for the occurrence of central nervous system inflammatory disease in different types of underlying autoimmune diseases during TNF-α inhibitor therapy (monoclonal antibodies vs. TNF-α receptor IgG fusion proteins)." (PMID 40676697, 2025). "This case highlights the diagnostic challenges in patients with autoimmune disease receiving anti-tumor necrosis factor (TNF) therapy and underscores the importance of considering multiple sclerosis (MS) in such clinical contexts." (PMID 41450349, 2025). "Tumor necrosis factor amplifies immune responses by stimulating the production of pro-inflammatory cytokines, yet excessive or chronic Tumor necrosis factor activity is a hallmark of autoimmune diseases." (PMID 41376630, 2025). "The participation of TNF-α in skin inflammation is very prevalent in such a way that most autoimmune diseases involving skin conditions are associated with it." (PMID 38674328, 2024). "Local anesthetics directly influence TNF-α production, predisposing it as candidate for the use suppressive drugs in downregulating the overactive inflammatory response in autoimmune diseases." (PMID 38674328, 2024). "Dysregulation of the production of TNF-α has been linked to various diseases, including autoimmune diseases, insulin resistance, and cancer." (PMID 38920613, 2024).
autoimmune disease (continued). "The activation of Th1 and Th17 T cells secondary to autoimmune diseases likely predisposes an individual to other autoimmune manifestations because of the hypersecretion of cytokines such as TNF-α, IL-23, and IL-17, which is discussed in greater detail below." (PMID 39697959, 2024). "TNF is a pivotal immune response cytokine, closely associated with the initiation and progression of various inflammatory and autoimmune diseases." (PMID 39026678, 2024). "Tuberculosis (TB) risk associated with tumor necrosis factor-alpha (TNF-α) antagonist therapy in patients with autoimmune diseases is a significant concern." (PMID 39639969, 2024). "TNF-α gene SNPs relative to the transcription site are shown to influence gene expression and are linked to various infectious and autoimmune diseases." (PMID 38883059, 2024). "The TNF-α 308 A allele is more involved in autoimmune diseases with higher transcriptional activity in comparison with the TNF-α-308G allele." (PMID 39202691, 2024). "Overproduction of TNF-α in chronic inflammatory conditions or autoimmune diseases can adversely affect bone health and elevate the risk of osteoporosis." (PMID 39200293, 2024). "The proinflammatory cytokine TNFα is produced by a variety of immune cell types, including macrophages, and is often implicated in the pathogenesis of inflammatory and autoimmune diseases." (PMID 38190378, 2024). "In light of these considerations, our systematic review and meta-analysis aim to comprehensively evaluate the risk of TB disease associated with TNF-α antagonist therapy across various autoimmune diseases and specific TNF-α antagonist drugs." (PMID 39639969, 2024). "TNF- α is a pro-inflammatory cytokine that has been linked with the pathophysiology of autoimmune disease and other inflammatory illnesses." (PMID 38266537, 2024). "Though traditionally associated with Th1 cells and a type 1 cytokine response, TNF-α has also been implicated in the differentiation of Th17 cells and promotion of IL-17 secretion by Th1 and Th17 cells in autoimmune disease." (PMID 39403935, 2024). "Here, we dissect the clinical aspects and overall outcomes of autoimmune diseases caused by anti-TNF-α therapies." (PMID 37175894, 2023). "The overproduction of TNF-α has been associated with multiple pathological processes, such as autoimmune diseases." (PMID 37370417, 2023). "TNF-α −308G/A polymorphism has been previously found to increase TNF-α transcription by six- to eightfold and has been associated with increased TNF-α production and development of several autoimmune diseases including ITP." (PMID 36802017, 2023). "Some increasing reports in the literature described TNF-targeted therapies causing autoimmune disease." (PMID 37835065, 2023). "Given the association of CTACK in other autoimmune diseases and the important role of other cytokines (e.g., IL-23, IL-7, and TNF-α) in AS, we believe that it is valuable to further explore the connection between CTACK levels and AS pathogenesis." (PMID 38173728, 2023). "For other autoimmune diseases like ankylosis spondylitis and psoriasis, treatment with TNF inhibitors was associated to an elevated risk for cancer and serious disease infection that includes TB." (PMID 38138078, 2023). "The association between polymorphisms in the TNF-α gene and various inflammatory conditions, including infections, autoimmune diseases, transplantation, and even cancers, has been described." (PMID 36979841, 2023). "Autoimmune diseases disorders of immune cells in the body, which cause immune cells to overactivate and produce a large number of inflammatory factors, such as TNF-α, IFN-γ, and IL-1β." (PMID 37089962, 2023). "The inappropriate or excessive activation of TNF-α signaling is associated with chronic inflammation, and it can eventually lead to the development of pathological conditions such as autoimmune diseases." (PMID 37189796, 2023).
autoimmune disease (continued). "Mechanistically, it is worth highlighting that dysregulated TNF expression has been linked to the development of pathological complications by acting on tissues, particularly in autoimmune diseases and IBD." (PMID 38137450, 2023). "TNF plays an important role in acute and chronic inflammatory diseases and many autoimmune diseases are associated with changes in TNF expression." (PMID 37959722, 2023). "Tumor necrosis factor α (TNF-α) is a multifunctional cytokine which can control the inflammatory process caused by bacterial and viral infections and promote autoimmune diseases as well as cancer." (PMID 35955688, 2022). "TNFα chronic expression is a hallmark of autoimmune disease (AI) widely treated with TNF antagonists." (PMID 36371231, 2022). "Excessive apoptosis of hepatocytes causes various liver diseases, and defective tumor necrosis factor (TNF)-induced apoptosis correlates with autoimmune diseases and liver diseases." (PMID 35874820, 2022). "Dysregulation in TNF-induced apoptosis is associated with many autoimmune diseases and various liver diseases." (PMID 34853447, 2022). "The most common underlying diseases in these patients were autoimmune diseases, whereas the commonest targeted therapy used was anti-TNFα monoclonal antibody." (PMID 35572995, 2022). "Protein-protein interactions between TNF and its receptor TNF-R1 are known to regulate the canonical TNF-induced NF-κB pathway and are therefore considered a pivotal therapeutic target for the treatment of TNF-associated autoimmune diseases, including cancer." (PMID 35222445, 2022). "In parallel, similar concerns have affected the use of tocilizumab in autoimmune diseases, revealing an even higher risk of bacterial infections with tocilizumab than with tumor necrosis factor inhibitors (TNFi)." (PMID 34406633, 2022). "We also noticed publications mentioned anti-TNF-α therapy had been increasingly associated with drug-induced autoimmune diseases, such as cutaneous vasculitis." (PMID 35455298, 2022). "TNF-α was found to be implicated in numerous autoimmune diseases and central nervous system diseases." (PMID 35949311, 2022). "Treatment with TNF inhibitors has been shown to lower the risk of cardiovascular disease among patients with autoimmune disease." (PMID 34576113, 2021). "Overexpression of TNF-α is widely associated with a series of autoimmune diseases, including rheumatoid arthritis, Crohn’s disease, and psoriasis." (PMID 34572435, 2021). "In latest studies, TANK was thought to respond to anti-TNF therapy in patients with autoimmune disease and as a candidate gene associated with hepatitis C virus clearance in both African and European Americans." (PMID 34540911, 2021). "A20-deficient mice develop a lethal autoimmune disease, characterized by increased responsiveness to TNF-α- and TLR-mediated signals as well as spontaneous inflammation of multiple organs." (PMID 34434197, 2021). "TNF-α plays a critical role in the pathogenesis of certain autoimmune diseases, and AA is associated with the increase in levels of IL-6." (PMID 34674748, 2021). "Overexpression of TNFα is associated with autoimmune diseases such as RA, psoriasis, lupus erythematosus, ankylosing spondylitis, and multiple sclerosis, among other effects." (PMID 34886761, 2021). "TNF-α gene polymorphisms are associated with autoimmune diseases, infection, cancers, and many other diseases, and TNF-α rs1800629 has been the most studied polymorphism." (PMID 34501555, 2021). "TNF-α was initially identified as a factor that can induce tumor cell necrosis, but was latterly found to be involved in the pathogenic process of autoimmune diseases as an important pro-inflammatory factor." (PMID 35126146, 2021). "TNF-α gene polymorphisms are associated with many diseases, such as infection, autoimmune diseases, rejection in organ transplantation, and so on." (PMID 34564376, 2021).
autoimmune disease (continued). "TNF-α is closely associated with iatrogenic diseases, pathogenic diseases, and monogenic and autoimmune diseases." (PMID 34667157, 2021). "Loss of TNFα-negative regulators such as miR-708 further propagates TNFα signaling, increasing the risk of transformation and autoimmune disease." (PMID 33776573, 2021). "TNF-α is a proinflammatory cytokine with pleiotropic effects in human disease and well-characterized pathogenic contributions to inflammatory and autoimmune diseases such as atherosclerosis and type 2 diabetes." (PMID 34576113, 2021). "Tumor necrosis factor inhibitors remain highly effective therapies for autoimmune diseases, and these associated inflammatory CNS events likely represent uncommon events." (PMID 32421186, 2020). "The expression profile of several genes in inflamed tissues have been associated with a response to anti-TNF agents in adults diagnosed with IBD or other autoimmune disorders." (PMID 32397546, 2020). "As a modest inflammatory effector, IL17 acts concertedly with other inflammatory mediators, such as TNFα and IFNγ, on pathogenic and protective processes in autoimmune disease and cancer." (PMID 32498703, 2020). "Polymorphisms located in the 5′ regulatory area of TNF-α gene at location -1031T/C have been associated with different inflammatory and autoimmune diseases." (PMID 32684830, 2020). "Investigation of interactions between a pro-inflammatory cytokine tumor necrosis factor (TNFα) and its receptor is required for the development of new treatments for autoimmune diseases associated with the adverse effects of TNFα." (PMID 32093269, 2020). "Is exposure to tumor necrosis factor inhibitors associated with risk of inflammatory demyelinating and nondemyelinating central nervous system events in patients with an autoimmune disease?" (PMID 32421186, 2020). "Anti-TNF-α therapy in patients with autoimmune disorders has been shown to increase the risk of TB reactivation; however, excessive TNF-α leads to increased macrophage necrosis that results in granuloma caseation." (PMID 32849525, 2020). "In this study population, TNF inhibitor exposure in patients with autoimmune diseases appeared to be associated with an increased risk of both inflammatory demyelinating and nondemyelinating CNS events." (PMID 32421186, 2020). "The Tag7 protein can be used to disrupt interactions between the TNFR1 receptor and its ligands for a treatment of inflammation in autoimmune diseases associated with the TNF expression." (PMID 32093269, 2020). "It has been reported that TNFα and IL-23 produced by DCs are pathogenic in several autoimmune disorders." (PMID 32899608, 2020). "Several single-nucleotide polymorphisms (SNPs) in the promoter region of the TNF-α gene can cause variations in the gene regulatory sites and act as risk factors for some autoimmune disorders as alopecia areata (AA) and vitiligo." (PMID 33370782, 2020). "Emerging evidences uncovered that major inflammatory cytokines tumor necrosis factor alpha (TNF-α) and interleukin 17 (IL-17) are associated with autoimmune diseases." (PMID 32265942, 2020). "In a study with systemic lupus erythematosus, a pro-inflammatory autoimmune disease, a higher TNF-α value was also associated with stronger depressive symptoms." (PMID 32528052, 2020). "Three TNF-associated single-nucleotide polymorphisms associated with higher risk of autoimmune diseases were used as instrumental variables." (PMID 32805626, 2020). "This study found that exposure to TNF inhibitors in patients with autoimmune diseases appeared to be associated with increased risk for inflammatory CNS events." (PMID 32421186, 2020). "Antibodies reducing the amount of soluble TNF capable to interact with its receptor are currently widely used to combat autoimmune diseases associated with the TNF overexpression." (PMID 32093269, 2020). "The SNP rs1800629 in TNF is linked to various autoimmune diseases, including CD, celiac disease, RA, and SLE." (PMID 32328064, 2020).
autoimmune disease (continued). "The -1031T/C polymorphisms in the 5′ regulatory region of TNF gene have been associated with many inflammatory and autoimmune diseases." (PMID 32684830, 2020). "Tumor Necrosis Factor (TNF) is a strong inducer of NF-kappa B transcription that has been implicated in the development of several autoimmune diseases, and correlates to the chronic inflammation that characterizes pSjS." (PMID 31480511, 2019). "Most researches of TNF-α gene polymorphism focus on genetic susceptibility to autoimmune diseases, inflammatory diseases, and cancers." (PMID 31652851, 2019). "A variety of autoimmune diseases are caused by an excessive immune response that is predominantly mediated by TNF-α." (PMID 31847135, 2019). "Various autoimmune diseases have been reported to associate with polymorphism of TNF-α gene promotor sequence." (PMID 30709060, 2019). "The TNFα gene promoter is known to be associated with TNFα protein levels, inflammation, outcome of infection, susceptibility to autoimmune diseases such as SS, and also with the most serious complication associated with SS, i.e. non-Hodgkin lymphoma." (PMID 30923465, 2019). "TNF-α is a key pathogenic mediator of several autoimmune diseases such as rheumatoid arthritis, Crohn’s disease, ulcerative colitis, psoriasis, psoriatic arthritis and ankylosing spondylitis." (PMID 30413827, 2019). "There is a documented association between Type 1 IFN signature, often implicated in the pathogenesis of pSS, and TNF-α in autoimmune disease." (PMID 31250166, 2019). "Therapeutic antibodies (Abs), Ab fragments, and fusion proteins directed against TNFα have revolutionized treatment of TNFα-associated autoimmune diseases and are currently used with great success." (PMID 30108591, 2018). "It has been implicated in the pathology of many autoimmune diseases, where elevated TNF levels are reported." (PMID 30206422, 2018). "This indeed is one of the main limitations of anti-TNF-α therapy that while effective in a wide variety of autoimmune disorders, it carries the risk of an impaired effective response to serious infections including tuberculosis." (PMID 30555461, 2018). "Although TNFα blockers have revolutionized therapy of autoimmune diseases, one of their major adverse effects is the significant risk of serious infections." (PMID 30108591, 2018). "Two of these clusters are highly enriched in pathways previously associated with autoimmune disease etiology (TNFα and IFNγ cytokine pathways)." (PMID 28982122, 2017). "An alternative to total TNF blockade is to use a selective TNFR1 inhibitor to target pathogenic TNF signaling in autoimmune disease conditions such as RA." (PMID 28824615, 2017). "While tumor necrosis factor alpha (TNF-α) inhibitors (TNFi) and other biologics are very effective against autoimmune diseases, they can also cause infectious diseases." (PMID 28158970, 2017). "Th17 cells differentiate in response to IL-1β, IL-6, IL-23, and TNF-α; secrete IL-17A, IL-17F, and IL-21; and play a critical pathogenic role in T cell-mediated autoimmune diseases." (PMID 28458638, 2017). "Several studies show that TNF-α gene promoter polymorphisms affect the susceptibility and/or severity of autoimmune diseases." (PMID 27652081, 2016). "TfH cells have been associated with autoimmune disease, but very little data exists on their role in RA, or the effect of TNF inhibitors on these cells." (PMID 28004828, 2016). "TNF produced by macrophages can promote angiogenesis, and chronic inflammation and vascular remodelling are intimately linked in autoimmune disease settings." (PMID 26765224, 2016). "Among these polymorphisms the −308G/A TNF-α promotor polymorphism has been associated several times with the the development of autoimmune diseases, however some discrepant results have been recorded." (PMID 27652081, 2016).